SIAH1 (siah E3 ubiquitin protein ligase 1)
Diseases named in the same sentence as SIAH1 in open-access papers (continued):
Sharing a sentence is not in itself a finding about the gene and the disease.
tumor (44 papers, 2005 to 2025). "Many of these additional mutated genes are pro-apoptotic, such as CASP8, BID, and SIAH1, suggesting that for relapse tumors to develop, tumor cells might need to acquire extra survival advantages." (PMID 25123191, 2014). "Predictably, images of the liver and H.E. staining showed that overexpression of SIAH1 inhibited tumor growth and intrahepatic metastasis, and immunohistochemistry was used to analyze the expression of SIAH1, ADRM1, UCHL5, FASN, and FSCN1." (PMID 39075049, 2024). "To validate our findings, we further demonstrated that tumor cells not only transcriptionally upregulated ZEB1 but also downregulated SIAH1 upon exposure to NK cells." (PMID 38191418, 2024). "In vivo experiments showed that SIAH1 overexpression or HMGCR inhibiter in combination with cisplatin inhibits tumor growth significantly." (PMID 37062828, 2023). "SIAH1 has been reported to act as a tumor suppressor during tumorigeneses, such as liver, ovarian, and breast." (PMID 37062828, 2023). "In vivo experiments showed that SIAH1 overexpression or using HMGCR knockdown retard tumor growth and enhanced the efficacy of cisplatin." (PMID 37062828, 2023). "In a vivo mouse model, SIAH1 knockdown promoted tumor proliferation, increased TC content, and the expression levels of HMGCR and ABCB1, consistent with in vitro results." (PMID 37062828, 2023). "SIAH1 reportedly behaves as a tumour suppressor during tumourigenesis by binding to numerous proteins, such as NcoR, TRAF, β-catenin, c-Myb, APC, and Kid, and thereby triggers their ubiquitylation and degradation via the ubiquitin–proteasome pathway." (PMID 35951361, 2022). "Herein we found that SIAH1 was decreased in EOC tumour tissues and cell lines and negatively correlated with the RPS3 levels." (PMID 35951361, 2022). "SIAH1 overexpression suppressed tumour cell growth, colony formation, invasion, metastasis, and cisplatin resistance in vivo and in vitro." (PMID 35951361, 2022). "SIAH1 overexpression resulted in a smaller tumours volume, fewer tumours, lower RPS3 protein expression, higher apoptosis rates and lower proliferation rates." (PMID 35951361, 2022). "Not surprisingly, PDTC enhanced the sensitization effect of SIAH1 and weakened the tumour-promoting effect of sh-SIAH1." (PMID 35951361, 2022). "Then, we focused on EOC and found that SIAH1 was remarkably decreased in tumor tissue derived from platinum-resistant (PFS < 6) patients compared with platinum-sensitive (PFS > 6) patients, as well as in EOC patients serum compared with healthy controls (HC)." (PMID 35273154, 2022). "As a member of the highly conserved family of E3 ubiquitin ligases, an increasing number of studies have revealed the key role of SIAH1 in cancer development and tumour resistance." (PMID 35951361, 2022). "According to other studies, SIAH1 is a tumor suppressor involved in PC pathogenesis by repressing CPSF1-mediated AR-v7 generation and is a key regulatory factor." (PMID 36744180, 2022). "In contrast to control cells, SW480/Siah1-shRNA cells showed faster tumor growth and remarkably bigger tumor volume (n = 6, P < 0.05)." (PMID 32082080, 2020). "Previous studies have shown that Siah1 is a target of MiRNAs and other proteins that are likely to affect the occurrence and progress of tumor." (PMID 32082080, 2020). "Siah E3 ubiquitin protein ligase 1 (Siah1) has been identified as a tumor suppressor gene and plays an important role in the development of malignant tumors." (PMID 32082080, 2020). "SIAH1 expression is negatively correlated with tumor malignancy in human cancers and can induce cell cycle arrest and suppress tumor formation." (PMID 30323224, 2018). "Siah1-mediated cytosolic β-catenin degradation is thought to have an overall tumor-suppressive effect." (PMID 28481365, 2017).
tumor (continued). "This was achieved by inhibiting SIAH1/2 E3 ligases, using both in vitro and in vivo tumor models of human pancreatic and lung cancer." (PMID 28784114, 2017). "SIAH1 has emerged as a tumor suppressor, inhibits cell proliferation and promotes apoptosis, by binding with APC and promoting the degradation of β-catenin." (PMID 27494869, 2016). "The human Siah1 and Siah2 isoforms share high sequence similarity but possess contrary roles in cancer, with Siah1 more often acting as a tumor suppressor while Siah2 functions as a proto-oncogene." (PMID 25202994, 2014). "In this study, we compared SIAH-1 mRNA and protein expression levels in normal and tumor tissues and cell lines." (PMID 20144232, 2010). "The staining with SIAH-1 in normal tissues revealed a similar punctuate pattern while in tumor tissues the expression was diffuse and was both cytoplasmic and nuclear." (PMID 20144232, 2010). "Further evidence implicating SIAH-1 in tumor suppression was shown to be related to its role in the regulation of β-catenin and hypoxia-inducible factor 1α (Hif-1α)." (PMID 20144232, 2010). "The human SIAH-1 is activated during tumor suppression and apoptosis, notably during physiological apoptosis occurring in the intestinal epithelium." (PMID 20144232, 2010). "Despite these efforts, the role of SIAH-1 as a tumor suppressor remains controversial since many efforts to identify putative mutations associated with tumoral processes have been almost unsuccessful." (PMID 20144232, 2010). "Therefore, when considering AGAP as a potential therapeutic for tumors, the concurrent use of SIAH1 inhibitors should be considered to mitigate the development of tumor resistance." (PMID 40080350, 2025). "Predictably, the mice tumor growth was significantly inhibited upon SIAH1 was overexpressed." (PMID 39075049, 2024). "Another study of Hu revealed the pro-metastatic effect of lncRNAs in the TME of LUAD and they found that lncR00963 loaded in LUAD cell-derived extracellular vesicles fostered tumor growth and metastasis by facilitating Siah1 degradation but suppressing Zeb1 degradation." (PMID 37566767, 2023). "Our results indicate that RPS3 may act as a tumour resistance promoter downstream of SIAH1 by promoting NF-κB-induced transcriptional activation, which is considered to contribute to EOC chemotherapy resistance." (PMID 35951361, 2022). "Together, our findings reveal a tumour suppressor function of SIAH1 and provide evidence showing that the SIAH1-RPS3-NF-κB axis may act as an appealing strategy for tackling treatment resistance in EOC." (PMID 35951361, 2022). "Furthermore, SIAH1 overexpression clearly enhanced the effect of cDDP on apoptosis and tumour growth, whereas SIAH1 knockdown had the opposite effect." (PMID 35951361, 2022). "Moreover, ectopic expression of RPS3 or depletion of RPS3 ubiquitination mediated by SIAH1 via the K214R mutant significantly impaired cisplatin-induced tumour suppression in cells stably expressing SIAH1." (PMID 35951361, 2022). "Overexpression of SIAH1 in U937 cells not only induce apoptosis but also led to tumor reversion." (PMID 33958005, 2021). "Although Siah1 has been identified to regulate proliferation, invasion and tumor growth in CRC, the possible molecular mechanism remains largely unknown." (PMID 32082080, 2020). "This notion is further supported by animal studies, which have shown Siah1 as a tumor-promoter." (PMID 28481365, 2017). "Furthermore, reduction of SIAH1 expression levels using RNA interference in HCC decreased tumor cell viability." (PMID 27377268, 2016).
tumor (continued). "Moreover, except for one sample, the number of Kid/KIF22 mRNA copies was consistently higher than the SIAH-1 mRNA copies in all normal tissues (with a median of 19,2 × 103) compared to their corresponding paired tumor tissues (median of 16,5 × 103)." (PMID 20144232, 2010). "Our previous observations led us to propose that SIAH-1 could have a role in tumor suppression and apoptosis." (PMID 20144232, 2010). "In addition, inhibition of nuclear SIAH-1 expression resulted in reduced tumor viability and deregulation of several genes involved in cell cycle regulation." (PMID 20144232, 2010). "In most cases, SIAH-1 mRNA is decreased in tumor tissues compared to their normal counterparts." (PMID 20144232, 2010). "However, previous studies indicate that downregulation of SIAH1 may impair the ability of tumor cells to adapt to stress conditions, thereby indirectly enhancing their sensitivity to apoptosis and inhibiting migration." (PMID 40080350, 2025). "Meanwhile, SIAH1 could decrease TC content and have a more muscular tumor suppressive effect." (PMID 37062828, 2023). "However, Siah1 is more often described as a tumour suppressor." (PMID 25202994, 2014). "SIAH1 was demonstrated to mediate the ubiquitination and degradation of β-catenin, ZEB1, Axin and Akt, which played key roles in tumor progression." (PMID 38734627, 2024). "SFMBT2 exerted an anti-tumor role in clear cell RCC cells, and HDAC3-mediated deacetylation promoted SIAH1-controlled ubiquitination of SFMBT2." (PMID 38734627, 2024). "Animal tumour formation experiments, verified the effects of SIAH1 and RPS3 on tumour growth and development in vivo." (PMID 35951361, 2022). "Our research confirmed that the exogenous overexpression of SIAH1 suppressed EOC cell proliferation, invasion, migration, drug resistance and tumour growth both in vitro and in vivo." (PMID 35951361, 2022). "Four of these intersecting genes, including PTPN1, CHSY1, SIAH1, and CCSAP, were correlated with tumor cell proliferation, migration, and invasion, and we therefore further confirmed their expression levels via RT-qPCR." (PMID 35610725, 2022). "Overall, these results indicate that a SIAH1–YBX-1-E2F5/YY1/RCC2 axis exists and that this axis plays an essential role in regulating the DDP sensitivity and tumor suppressor function of SIAH1." (PMID 35273154, 2022). "It was found that the expression level of KCTD12, SIAH1, TRIM58, UBE2S, and UBE2T were significantly decreased in tumor tissue compared with the normal tissue, but TRIM47 was upregulated." (PMID 36534449, 2022). "Compared with the SIAH1 + FLAG-RPS3 group, transfection with SIAH1 + FLAG-RPS3(K214R) resulted in a larger tumour volume, more tumours, higher RPS3 protein expression, lower apoptosis rates and higher proliferation rates." (PMID 35951361, 2022). "Functional studies revealed that ectopic overexpression of SIAH1 alleviated DDP resistance and suppressed invasion, proliferation, and tumor growth of EOC cells both in vitro and in vivo, and exogenous knockdown of SIAH1 generated the opposite effects." (PMID 35273154, 2022). "Consistently, our study showed that SIAH1 overexpression decreased YBX-1 expression and inhibited the ability of YBX-1 to promote proliferation, invasion, tumor growth, and DDP resistance in EOC cells, thus enhancing the chemosensitivity of EOC cells." (PMID 35273154, 2022). "In concordance with these reports, our study found that SIAH1 was downregulated in EOC patients and tumor tissue derived from DDP-sensitive EOC patients compared with DDP-resistant EOC patients." (PMID 35273154, 2022).
tumor (continued). "In the present study, we confirmed that exogenous overexpression of Siah1 suppressed CRC cells proliferation, invasion and tumor growth both in vitro and in vivo." (PMID 32082080, 2020). "In a hypoxic environment, HIPK2 down-regulates the activity of HIF-1, Siah1, Siah2, VEGF and WBS-1 to inhibit tumor angiogenesis." (PMID 28107201, 2017). "This study has attempted to further our understanding by analyzing mRNA and protein expression of SIAH-1 and it's substrate Kid/KIF22, in both normal and tumor tissues." (PMID 20144232, 2010). "In the present study we observed a deregulation of both SIAH-1 and Kid/KIF22 proteins in tumor breast tissues, changing from a localized expression to a more diffuse pattern throughout the cell." (PMID 20144232, 2010). "SIAH-1 and Kid/KIF22 protein expression were compared in normal and tumor breast tissues obtained from the same patient." (PMID 20144232, 2010). "Immunofluorescence microscopy shows that the intracellular distribution of SIAH-1 and Kid/KIF22 appears to be modified in human tumor tissues compared to normal controls." (PMID 20144232, 2010). "Comparing non-metastatic tumor cluster 1 versus either cluster 12 or 14, we not only found lower expression of TNFSF9 (encoding 41BBL) but also higher levels of SIAH1 which is an E3 ligase that was found to be downregulated during TGFB-induced EMT." (PMID 38191418, 2024). "Coherently, our study demonstrated that SIAH1 overexpression reduced HMGCR expression and inhibited the ability of HMGCR to promote proliferation, migration, tumor growth, and DDP resistance in A549/DDP cells, thereby enhancing the chemosensitivity of A549/DDP cells." (PMID 37062828, 2023). "In addition, in contrast to the tumor-promoting role of CacyBP, Siah-1 expression tended to be downregulated in HCC tissues, and patients with reduced Siah-1 expression showed a lower OS and disease-free survival (DFS)." (PMID 37968706, 2023). "Consistently, RP11 decreased the expression of Siah1 and Fbxo45 in HCT-15 tumour xenografts." (PMID 30979372, 2019). "The upregulation of SIAH1, similar to RAB5B, may function as a defense mechanism in tumor cells." (PMID 40080350, 2025). "Other analyzed organs displayed a less systematic variation between normal and tumor tissues (e.g. lung), however all the tumoural specimens displayed the heterogenous pattern, with groups of tumor cells expressing very high levels of SIAH-1 and others without any detectable expression." (PMID 20144232, 2010). "Interestingly, ICP0 itself is targeted for degradation by SIAH-1, demonstrating the complexity of functional consequences of post-translational modification on PML regulation and the close interplay between anti-viral as well as tumor-suppressive defense mechanisms." (PMID 38467608, 2024). "In addition, the SIAH1 protein levels were clearly increased in tumours obtained from patients with progression-free survival (PFS) > 6 months (clinically described as cDDP sensitive), whereas its expression was reduced in tumours obtained from patients with PFS < 6 months (cDDP resistant)." (PMID 35951361, 2022). "The findings concord with our in vitro results, showing a strong negative correlation between SIAH1 and HMGCR in tumor tissues." (PMID 37062828, 2023). "The results are consistent with our in vitro findings, showing a strong negative correlation between SIAH1 and YBX-1 in tumor tissues." (PMID 35273154, 2022).
cancer (33 papers, 2008 to 2026). A tumor composed of atypical neoplastic, often pleomorphic cells that invade other tissues. "In mammals, SIAH1 targets various proteins, including itself, for ubiquitylation and proteasomal degradation, participating in various biological processes and implicated in diseases such as cancer." (PMID 40349774, 2025). "In addition, SIAH1 has been implicated in cancer-related signalling pathways, including cell apoptosis (β-catenin, Sec6), DNA damage repair (c-Abl, HIPK2, and TRF2) and the in vivo hypoxia response (PHD3, HIF-1a, and IL-17)." (PMID 35951361, 2022). "Moreover, a number of studies have linked SIAH1 expression with disease progression in human cancer." (PMID 27377268, 2016). "The mRNA and protein levels of SIAH1 exert tumour‐inhibitory effects and have been reported as downregulated in cancer." (PMID 38842124, 2024). "It has been reported that PERK/ATF4 induces transcription and expression of the ubiquitin ligases SIAH1/2 in cancer cell lines.To identify the link among PERK, ATF4, SIAH2 and HIPK2, knockdown of genes by siRNA was carried out." (PMID 37268944, 2023). "Emerging a growing number of studies have shifted the focus to the effect of SIAH1 on cancers recently." (PMID 35273154, 2022). "Data from The Cancer Genome Atlas (TCGA) show that SIAH1 gene downregulation is a common genetic alteration in different kinds of cancers." (PMID 35273154, 2022). "More importantly, Siah1 mediates the ubiquitination of target proteins that regulate general functions necessary for tumorigenesis and the progression of cancer, such as cell growth arrest, apoptosis, and DNA repair, etc.." (PMID 32082080, 2020). "By screening for factors responsible for the stability of Zeb1 in cancer cells, we confirm that the downregulation of Siah1 and Fbxo45 mediates the RP11-induced stabilization of Zeb1 in CRC cells." (PMID 30979372, 2019). "Additional work will be conducted to examine the interplay between SIAH3 and SIAH1/SIAH2 in oncogenic K-RAS-driven human cancers in the future." (PMID 28784114, 2017). "H&E staining and fluorescence microscopy showed marked induction of ETS2 and Siah1 in adenocarcinoma samples (n=10) compared to non-cancer tissues (n=10)." (PMID 28481365, 2017). "In diverse types of cancer, SIAH1 has a dual function in RAS, estrogen, DNA-damage, and hypoxia pathways therefore it is considered as an attractive anticancer drug target." (PMID 27377268, 2016). "Because of its relevant role in migration of cancer cells we next focused in the analysis of the SIAH1 protein." (PMID 27377268, 2016). "The different function of Siah1 and Siah2 in cancer is likely due to the ubiquitination of distinct substrates." (PMID 25202994, 2014). "Given the different roles of Siah1 and Siah2 in cancer and their different cellular functions, it is important to understand the structural basis of their substrate specificity and to design Siah2 specific inhibitors." (PMID 25202994, 2014). "Evidence from in vitro, in vivo, and patient sample studies describe opposite roles for Siah1 and Siah2 in cancer progression, metastasis, and therapeutic responses." (PMID 25202994, 2014). "The different roles of Siah1 and Siah2 in cancer are likely mediated through the ubiquitination of distinct substrates." (PMID 25202994, 2014). "For instance, the expression levels of Siah1 have been reported to be downregulated in various cancers." (PMID 25202994, 2014). "The Siah1 and Siah2 E3 ubiquitin ligases play an important role in diverse signaling pathways and have been shown to be deregulated in cancer." (PMID 25202994, 2014). "SIAH3 appears to be an attractive target for further investigation as its active homologs, SIAH1 and SIAH2, are known to be downstream effectors of the KRAS pathway and have been shown to be associated with cancer progression and poor prognosis in multiple cancers." (PMID 40243415, 2025).